RNU7-82P (RNA, U7 small nuclear 82 pseudogene)
Synonyms: U7.82; RNU7-163P
Gene: Small nuclear RNA gene on chromosome 3 (163,470,205 to 163,470,266, reverse strand). Ensembl gene ENSG00000238924.
Homologues: Orthologues: chimpanzee U7 (98% identical), macaque U7 (85% identical). Paralogues in human: RNU7-174P (85% identical), RNU7-121P (84% identical), RNU7-152P (84% identical), RNU7-167P (84% identical), RNU7-35P (84% identical), RNU7-57P (84% identical), RNU7-62P (84% identical), U7 (84% identical), RNU7-113P (82% identical), RNU7-124P (82% identical), RNU7-187P (82% identical), RNU7-40P (82% identical), and 140 more.